ESCO1 (establishment of sister chromatid cohesion N-acetyltransferase 1)
Description:
Acetyltransferase required for the establishment of sister chromatid cohesion. Couples the processes of cohesion and DNA replication to ensure that only sister chromatids become paired together. In contrast to the structural cohesins, the deposition and establishment factors are required only during S phase. Acts by mediating the acetylation of cohesin component SMC3.
Synonyms: EFO1; KIAA1911; ESO1; A930014I12Rik; CTF; ECO1
Tractability: Small molecule: a structure with a bound ligand is known. PROTAC: UniProt records ubiquitination sites on it; ubiquitination databases record sites on it.
Gene: Protein-coding gene on chromosome 18 (21,529,041 to 21,600,966, reverse strand). Ensembl gene ENSG00000141446.
Subcellular location: Nucleus; Chromosome
Pathways (Reactome):
Cell Cycle: Establishment of Sister Chromatid Cohesion
Gene Ontology:
Molecular function: acetyltransferase activity; N-acetyltransferase activity; protein-lysine-acetyltransferase activity; zinc ion binding
Biological process: peptidyl-lysine acetylation; post-translational protein acetylation; regulation of DNA replication; sister chromatid cohesion
Cellular component: chromatin; chromosome; nucleus; nucleoplasm
Genetic constraint (gnomAD): Loss-of-function variants: 27 observed, 72.81 expected, observed/expected ratio (o/e) 0.37, 90% interval 0.27 to 0.51. The upper end of that interval is the gene's LOEUF score, 0.51, which puts it in group 2 of 6, group 1 being the genes least tolerant of losing a copy. Missense variants: 820 observed, 968.96 expected, observed/expected ratio (o/e) 0.85, 90% interval 0.8 to 0.9. Synonymous variants: 327 observed, 329.89 expected, observed/expected ratio (o/e) 0.99, 90% interval 0.9 to 1.09.
Homologues: Orthologues: chimpanzee ESCO1 (99% identical), macaque ESCO1 (96% identical), dog ESCO1 (86% identical), pig ESCO1 (85% identical), rabbit ESCO1 (85% identical), rat Esco1 (78% identical), mouse Esco1 (77% identical), tropical clawed frog esco1 (41% identical), zebrafish esco1 (27% identical). Paralogues in human: ESCO2 (23% identical), REV1 (10% identical), POLI (7% identical), POLK (7% identical), POLH (6% identical).
Diseases named in the same sentence as ESCO1 in open-access papers:
ESCO1 is named in the same sentence as 14 diseases in open-access papers, as found by Europe PMC text mining. Sharing a sentence is not in itself a finding about the gene and the disease. The quoted sentences say what the papers report.
Roberts syndrome (4 papers, 2012 to 2022). "In humans, mutations in ECO1 orthologs (termed ESCO1/EFO1 and ESCO2/EFO2) collectively correlate with numerous forms of cancer, including melanoma and prostate cancer, and a severe developmental abnormality called Roberts Syndrome (RBS)." (PMID 33373396, 2020).
cervical cancer (3 papers, 2025 to 2026). A primary or metastatic malignant neoplasm involving the cervix. "These novel findings reveal oncopeptide TUBORF and its acetyltransferase ESCO1 as important regulators of ferroptosis and tumorigenesis during cervical cancer pathogenesis and establish the scientific basis for targeting these molecules for treating CC." (PMID 39836502, 2025). "Currently, we indicated that ESCO1 was highly expressed in cervical cancer tissues." (PMID 39836502, 2025). "Oncogenic kinases and methyltransferases including AURKA, AURKB, ESCO1, NEK6, and PRMTs that promote carcinogenesis are notably upregulated in cervical cancer." (PMID 41562705, 2026). "As a lysine acetyltransferase, ESCO1 is highly expressed in a variety of tumors, including bladder cancer, prostate cancer, and endometrial cancer; however, its role in cervical cancer has not been elucidated." (PMID 39836502, 2025).
endometrial cancer (3 papers, 2014 to 2025). Primary or metastatic malignant neoplasm involving the endometrium (mucous membrane that lines the endometrial cavity). "For example, up‐regulated ESCO1 was found in bladder cancer, prostate cancer, and endometrial cancer, which was linked with the cellular behaviors." (PMID 31944408, 2020).
endometrial tumors (1 paper, 2014). "We uncovered nonsynonymous somatic mutations in ESCO1, CHTF18, and MRE11A in, respectively, 3.7% (4 of 107), 1.9% (2 of 107), and 1.9% (2 of 107) of endometrial tumors." (PMID 23755103, 2014). "Our study uncovered nonsynonymous somatic mutations in ESCO1, CHTF18, and MRE11A in a subset of human endometrial tumors." (PMID 23755103, 2014). "This is the first report of somatic mutations within ESCO1 and CHTF18 in endometrial tumors and of MRE11A mutations in microsatellite-stable endometrial tumors." (PMID 23755103, 2014).
cancer (10 papers, 2019 to 2025). A tumor composed of atypical neoplastic, often pleomorphic cells that invade other tissues. "ESCO1 expression is also linked to cancer progression and metastasis." (PMID 35409426, 2022). "Upregulation of ESCO1 inhibited ferroptosis and promoted the malignant proliferation of cancer cells." (PMID 39836502, 2025).
tumor (1 paper, 2025). "As expected, silencing TUBORF or ESCO1 potentiated the ability of paclitaxel to inhibit tumor weight and size." (PMID 39836502, 2025).
ESCO1 also shares sentences with these, for which no sentence is quoted: prostate carcinoma (3 papers); bladder cancer (2); Cornelia de Lange syndrome (1); glioma (1); infection (1); intellectual disabilities (1); melanoma (1); peripheral neuropathy (1).